TERT (telomerase reverse transcriptase)
Diseases named in the same sentence as TERT in open-access papers (continued):
Sharing a sentence is not in itself a finding about the gene and the disease.
kidney cancer (6 papers, 2018 to 2024). Primary or metastatic malignant neoplasm involving the kidney. "The telomerase protein is coded by the gene TERT and increased TERT RNA levels have been associated with disease relapse in Wilms tumor, the most common kidney cancer of childhood." (PMID 35406427, 2022). "TERT was detected in kidney cancers both from the US cohort (KICH) and the European cohort (RECA) which further demonstrated the reproducibility of HYENA." (PMID 39051548, 2024). "Studies suggest that the TERT mutation and germline mutations of FLCN are associated with both kidney cancer and PTC." (PMID 30046434, 2018).
lung disease (6 papers, 2011 to 2023). "In the largest series of TERT mutations published to date, the mean age of 134 carriers was 51 years; 50% of these heterozygotes had pulmonary disease but only 16% had haematological abnormalities." (PMID 21931702, 2011). "Telomere length, RTEL1 and TERT expression may serve as potential biomarkers related to silica exposure and may offer insight into the molecular mechanism of silica-induced lung disease and tumorigeneses." (PMID 29230030, 2017).
Obesity (6 papers, 2010 to 2025). Accumulation of substantial excess body fat. "In the present study, we found that DNA methylation fractions of the TERT promoter were increased in children with obesity." (PMID 33413203, 2021). "The methylated fractions in 13 of 25 CpG sites in the TERT promoter were increased by approximately 3 to 35% in the children with obesity compared to the normal weight children." (PMID 33413203, 2021). "In summary, preschool children with obesity had shorter leukocyte telomeres, accompanied by DNA hypermethylation at the TERT promoter." (PMID 33413203, 2021). "This study aimed to investigate changes in telomere length and telomerase reverse transcriptase (TERT) DNA methylation, and further to determine their correlation with n-3 polyunsaturated fatty acids (PUFAs) in preschool children with obesity." (PMID 33413203, 2021). "The data presented here suggested that DNA hypermethylation at the TERT promoter might reduce mRNA expression of TERT and its activity, and thus lead to telomere attrition in obesity." (PMID 33413203, 2021). "Therefore, this study aimed to investigate changes in telomere length and TERT promoter DNA methylation, and further to determine their correlation with n-3 PUFAs in preschool children with obesity." (PMID 33413203, 2021). "The aim of this study was to investigate the biological actions regulated by leptin, the obesity biomarker molecule, and its receptors in HCC and the correlation between leptin and human telomerase reverse transcriptase (hTERT), a known mediator of cellular immortalization." (PMID 20723213, 2010).
oral cancer (6 papers, 2016 to 2025). "We also confirmed the previously reported oral cancer susceptibility loci at the TERT-CLMPT1L locus on 5p15.33, thet 4q23 ADH1B locus, and the LAMC3 locus on 9q34.12 in Taiwanese populations." (PMID 36769103, 2023). "Among the oral cancer samples, the TERT promoter hotspot mutations were frequent, while the C228T mutation (69.2%) was twice as frequent as the C250T (30.8%)." (PMID 36979671, 2023). "The results of our systematic review and meta-analysis on 21 studies and 1698 patients with oral cancer demonstrate for the first time and based on evidence that TERT upregulation is predictive of the risk of death in patients with oral cancer, i.e., overall survival." (PMID 35954336, 2022). "In conclusion, our findings indicate that TERT upregulation is a prognostic indicator of poor survival in oral cancer." (PMID 35954336, 2022). "This meta-analysis also reinforces the need for further research on the potential applications of TERT as a therapeutic target in oral cancer." (PMID 35954336, 2022). "In conclusion, the immunohistochemical determination of TERT overexpression is an indicator of poor survival in oral cancer and probably should be incorporated in the prognostic evaluation of these patients." (PMID 35954336, 2022). "As histone deacetylase inhibitor FR901228 induces a significant increase in TERT expression in oral cancer cell lines, it is possible that the latter is epigenetically controlled in HNSCC through changes in DNA methylation or histone acetylation." (PMID 27501725, 2016). "The CAL27 cell line carried the TERTp C228T mutation and TERT mRNA expression was 11–15 folds higher compared to non-mutated oral carcinoma cell lines." (PMID 41487579, 2025). "Some have hypothesized that TERT provides oral cancer cells with invasion capability by modulating cathepsin D, MMP2, and MMP9 which, in turn, degrade the extracellular matrix and collagen IV, essential for basement membrane stability and integrity." (PMID 27501725, 2016). "The frequency of TERT mutations was also independent of HPV tumor status in oral cancer." (PMID 36979671, 2023). "Consequently, and based on the previous comments, we carried out a systematic review and meta-analysis on the clinical and prognostic significance of the replicative immortality linked to telomerase activation, essentially by activation of one of its most relevant components—TERT—in oral cancer." (PMID 35954336, 2022). "Silencing TERT, instead, leads to the inhibition of Wnt/β-catenin signaling and the suppression of EMT in oral cancer." (PMID 27501725, 2016). "Immunohistochemistry results showed an oral cancer mortality rate 3.01 times higher in patients who overexpressed TERT vs. those who did not." (PMID 35954336, 2022).
soft tissue sarcoma (6 papers, 2014 to 2025). A malignant neoplasm arising from muscle tissue, adipose tissue, blood vessels, fibrous tissue, or other supportive tissues excluding the bones. "The overall prevalence of TERT promoter hotspot mutations was low in the comprehensive series of soft tissue sarcomas examined in this study (36/341; 10.5%)." (PMID 24726063, 2014). "The occurrence of TERT promoter mutations has been well described in soft tissue sarcomas (STS)." (PMID 29463038, 2018). "Conversely, TERT promoter mutations are rare in soft tissue sarcomas and have not been reported in any unequivocal rhabdomyosarcomas." (PMID 40090763, 2025).
Stroke (6 papers, 2015 to 2024). Sudden impairment of blood flow to a part of the brain due to occlusion or rupture of an artery to the brain. "Genetic polymorphisms of telomere-related genes such as ACYP2, TSPYL6, and TERT have been reported to be associated with stroke." (PMID 29383136, 2017). "TERT deficiency exacerbates BBB dysfunction, inflammatory responses, and oxidative stress in stroke mice, leading to neurological deficits and increased infarct volumes." (PMID 37728582, 2024). "We hypothesize that TERT positively affects aged animals with stroke." (PMID 37728582, 2024). "There is still great research value for the four more meaningful stroke-related proteins (STAT3, MMP2, ESR1, TERT) in this study, and pointed out the direction for our further research." (PMID 36133785, 2022).
anaplastic meningioma (5 papers, 2019 to 2025). A WHO grade III meningioma characterized by the presence of malignant morphologic features, including malignant cytology and a very high mitotic index (20 or more mitoses per ten high power fields). "Histopathological analysis confirmed the recurrence as anaplastic meningioma with telomerase reverse transcriptase (TERT) promoter C250T mutation, CNS WHO Grade 3—marking the first documented association of this mutation with spinal CM." (PMID 41013491, 2025). "This case report details a rare case of cervical CM that recurred as anaplastic meningioma with a TERT mutation, representing the first reported instance of an association between spinal CM and this genetic alteration." (PMID 41013491, 2025). "While not identified within our matched tumor sample, prior genetics work have linked CDK2NA mutations to decreased survival in anaplastic meningioma, and TERT promoter mutations to decreased OS in both higher grade meningioma and across tumor grades." (PMID 31191822, 2019). "TERT promotor mutation status was available in 67/95 patients (70.5%), revealing TERT promotor mutations in six of 67 patients (9.0%) and leading to a re-classification as anaplastic meningioma WHO grade 3 in three cases." (PMID 38581569, 2024). "Nine of 95 tumors (9.5%) corresponded to anaplastic meningiomas WHO grade 3, including six patients harboring TERT promoter mutations." (PMID 38581569, 2024). "The integrated diagnoses of the initial lesions (under consideration of the TERT promoter and CDKN2A/B deletion) were three CNS WHO grade 1 tumors (microcystic, meningothelial and papillary), one CNS WHO grade 2 tumor (atypical) and one anaplastic meningioma, CNS WHO grade 3." (PMID 36641486, 2023).
Anxiety (5 papers, 2016 to 2025). Intense feelings of nervousness, tension, or panic often arise in response to interpersonal stresses. "Accordingly, this model suggests that individuals experience heightened anxiety when they appraise a situation as threatening, such as having a TERT mutation, and that they lack the coping skills to deal with it." (PMID 40940948, 2025). "Male TERT-tg mice exhibit impaired social behavior, increased anxiety-like behavior, and lowered seizure threshold, while female TERT-tg mice do not." (PMID 29922129, 2018). "Moreover, mice lacking TERT displayed noticeable changes in anxiety‐related behaviors." (PMID 38421107, 2024).
Burkitt lymphoma (5 papers, 2016 to 2025). A rare form of malignant mature B-cell non-Hodgkin lymphoma. "Remarkably, TERT inhibition in EBV-positive Burkitt’s lymphomas and lymphoblastoid cell lines caused an enhancement of the apoptotic effect induced by the antiviral therapy-opening opportunities for new therapeutic protocols including TERT inhibitors to treat EBV-related malignancies." (PMID 36358677, 2022). "Given the pivotal role of MYC in EBV-driven B-cell proliferation and Burkitt’s lymphoma, its expression following treatment with TERT inhibition was analysed in more detail." (PMID 37345011, 2023). "Our aim was to characterize the biological effects of TERT inhibition by BIBR on EBV-immortalized lymphoblastoid cell lines (LCLs) and fully transformed Burkitt's lymphoma (BL) cell lines." (PMID 28032863, 2016).
chronic hepatitis (5 papers, 2007 to 2025). An active inflammatory process affecting the liver for more than six months. "As hepatitis virus (HBV or HCV) infection is a major etiological feature of Chinese BTC patients 42, mutations in TERT and its promoter regions were more common among our BTC patients with a chronic hepatitis history." (PMID 33754015, 2021). "Our data demonstrating telomerase activation in regenerating pig liver tissue are consistent with previous findings in patients with chronic hepatitis showing TERT expression and telomerase activation in regenerative nodules." (PMID 17605788, 2007). "During the progression of chronic hepatitis, the aberrant upregulation of TERT may promote carcinogenesis through various mechanisms." (PMID 40213897, 2025).
epilepsy (5 papers, 2023 to 2024). A brain disorder characterized by episodes of abnormally increased neuronal discharge resulting in transient episodes of sensory or motor neurological dysfunction, or psychic dysfunction. "Age (odds ratio [OR] = 1.06, P = 0.01) and epilepsy (OR = 5.73, P = 0.03) were revealed to be important predictors of TERT mutation in the subsequent multivariate logistic regression model." (PMID 38982347, 2024). "In particular, the impact of genetic alterations like TERT promotor mutations on tumor-related epilepsy remains unclear." (PMID 38581569, 2024). "Notably, the multivariate analysis further reinforced the importance of age and epilepsy as predictors of TERT mutation status." (PMID 38982347, 2024). "Notably, males and epilepsy are prevalent factors that increase the likelihood of mutations in both IDH and TERT promoters." (PMID 38982347, 2024). "Despite the presence of seizures in many IDHwt hLGG patients, there are no definitive data on the association between TERT and epilepsy." (PMID 38067243, 2023).
esophageal adenocarcinoma (5 papers, 2022 to 2025). A malignant tumor with glandular differentiation arising predominantly from Barrett mucosa in the lower third of the esophagus. "Promoter mutations of the TERT gene frequently occur in different cancers, including esophageal adenocarcinoma, and are associated with tumor aggressiveness and poor prognosis." (PMID 39744560, 2025). "In this study, we describe the TERT amplification status as an independent risk factor for worse survival in patients diagnosed with esophageal adenocarcinoma at pT1N0-3 tumor stage, encompassing cases involving tumor infiltration of the lamina propria, muscularis mucosae, and/or submucosa." (PMID 37848472, 2023). "In Barrett’s esophagus, the TERT expression reduction associated with the increased expression of Caspase-3, which has a central role in apoptosis, suggests that Barrett’s epithelium may be a microenvironment prone to DNA instability." (PMID 36078072, 2022). "This study aims to shed light on the relationship between TERT amplification status and patient survival in individuals diagnosed with esophageal adenocarcinoma." (PMID 37848472, 2023). "Additionally, telomerase reverse transcriptase (TERT) expression was reduced in Barrett’s esophagus, while the expression of HSP 105 and Caspase-3 was increased." (PMID 40149421, 2025). "However, the implications for survival stemming from TERT amplification in esophageal adenocarcinoma remain unexplored." (PMID 37848472, 2023). "Therefore, this study seeks to unravel the role of copy number gain of TERT in patients with esophageal adenocarcinoma." (PMID 37848472, 2023). "Based on our findings, we put forth the proposition that evaluating the TERT amplification status may serve as a valuable tool in identifying a specific subgroup of patients, namely those with TERT amplification and pT1N0-3 tumor-stage esophageal adenocarcinoma." (PMID 37848472, 2023). "However, it’s important to note that these findings may not be applicable to every patient with esophageal adenocarcinoma, as substantial variations in the prevalence of TERT mutations based on race and sex have been previously reported depending on the cancer entity." (PMID 37848472, 2023).
Ewing sarcoma (5 papers, 2019 to 2025). A small round cell tumor that lacks morphologic, immunohistochemical, and electron microscopic evidence of neuroectodermal differentiation. "Takahashi and his colleagues reported that EWSR1–ETS fusion activated hTERT expression in Ewing’s sarcoma by recruiting p300 to TERT promoter in an ETS factor binding site-independent manner." (PMID 34221969, 2021). "Moreover, we checked the expression of several genes that were previously reported to be affected by YK-4-279 in Ewing’s sarcoma and found that the expressions of TERT and UBE2C (Ubiquitin Conjugating Enzyme E2-C) were reduced after YK-4-279 treatment in our cell lines." (PMID 34221969, 2021).
fibrosis (5 papers, 2022 to 2025). the formation of excess fibrous connective tissue in an organ or tissue in a reparative or reactive process. "TERT gene study revealed that six (40%) of the fibrosis group wasnormal, while five were heterozygous (33.3%)." (PMID 36912407, 2023). "Mutations in the genes encodingtelomerase reverse transcriptase (TERT) and mucin5B (MUC5B) are well-known risk factors forpulmonary fibrosis." (PMID 36912407, 2023). "The study found that the expression of KLF4 and TERT in IPF patients and fibrosis mouse model AT2 is decreased, while the overexpression of KLF4 can increase the expression of TERT and telomerase activity." (PMID 36825939, 2023).
gastric tumors (5 papers, 2015 to 2024). "Additionally, it has been discovered that the TERT hypermethylation tumor region (THOR), which is linked to elevated TERT expression and accelerates the development of pancreatic and stomach tumors, is present in these diseases." (PMID 38819232, 2024). "Therefore, we confirmed that TERT expression was also significantly regulated by galectin-3 in in vivo gastric tumors." (PMID 27494887, 2016). "The presence of co-activation of TERT and YY1 was determined in a subset of gastric tumors." (PMID 34497757, 2021).